FAM72B (family with sequence similarity 72 member B)
Synonyms: RP11-439A17.6; p17
Tractability: Antibody: the Human Protein Atlas places it where antibodies can reach. PROTAC: ubiquitination databases record sites on it.
Gene: Protein-coding gene on chromosome 1 (121,167,646 to 121,185,539, reverse strand). Ensembl gene ENSG00000188610.
Subcellular location (Human Protein Atlas): Vesicles; Cytosol; Plasma membrane
Gene Ontology:
Cellular component: cytosol
Genetic constraint (gnomAD): Loss-of-function variants: 3 observed, 6.71 expected, observed/expected ratio (o/e) 0.45, 90% interval 0.2 to 1.15. That is too few expected variants to judge how well the gene tolerates losing a copy. Missense variants: 37 observed, 63.14 expected, observed/expected ratio (o/e) 0.59, 90% interval 0.45 to 0.77. Synonymous variants: 5 observed, 19.6 expected, observed/expected ratio (o/e) 0.26, 90% interval 0.13 to 0.54.
Homologues: Orthologues: chimpanzee FAM72A (99% identical), macaque FAM72A (99% identical), guinea pig Fam72a (93% identical), mouse Fam72a (89% identical), rat Fam72a (89% identical), dog FAM72A (78% identical), zebrafish FAM72A (62% identical), tropical clawed frog fam72a (53% identical). Paralogues in human: FAM72A (99% identical), FAM72D (97% identical), FAM72C (97% identical).
Diseases named in the same sentence as FAM72B in open-access papers:
FAM72B is named in the same sentence as 24 diseases in open-access papers, as found by Europe PMC text mining. Sharing a sentence is not in itself a finding about the gene and the disease. The quoted sentences say what the papers report.
neuroblastoma (2 papers, 2022 to 2025). Neuroblastoma (NB) is the most common solid, extracranial childhood tumor. "Preliminary studies uncover that family with sequence similarity 72B (FAM72B) was upregulated in the nervous system, neuroblastoma, and breast adenocarcinoma." (PMID 35707363, 2022). "Previous studies reported that FAM72B was upregulated in the nervous system, neuroblastoma, and breast adenocarcinoma." (PMID 35707363, 2022).
prostate carcinoma (2 papers, 2021 to 2022). A carcinoma that arises from epithelial cells of the prostate gland. "FAM72B was identified as a member of a 7-gene signature in prostate cancer and correlated with poor prognosis in patients with prostate cancer." (PMID 35707363, 2022).
acute myeloid leukemia (1 paper, 2025). Acute myeloid leukemia (AML) is a group of neoplasms arising from precursor cells committed to the myeloid cell-line differentiation. "FAM72B was studied at the single-cell level in eight types of cancer, including retinoblastoma (RB), BRCA, uveal melanoma (UM), ALL, melanoma (MEL), acute myeloid leukemia (AML), GBM, and LUAD, with significant correlations observed only in RB, BRCA, UM, ALL, and MEL." (PMID 41153357, 2025).
clear cell renal cell carcinoma (1 paper, 2025). "Existing studies have indicated that FAM72B is overexpressed in various tumor types, including OSCC, clear cell renal cell carcinoma (ccRCC), LUAD, and glioblastoma multiform (GBM)." (PMID 41153357, 2025).
colorectal adenocarcinoma (1 paper, 2025). The most common type of colorectal carcinoma. "The results showed that patients with BRCA and colorectal adenocarcinoma harboring FAM72B genetic alterations had a poorer prognosis." (PMID 41153357, 2025).
lung adenocarcinoma (1 paper, 2022). A carcinoma that arises from the lung and is characterized by the presence of malignant glandular epithelial cells. "Nevertheless, the prognostic value of FAM72B expression and its function in the immune microenvironment of lung adenocarcinoma (LUAD) currently remains elusive." (PMID 35707363, 2022). "Logistic regression analyzed the correlation between FAM72B expression and the clinical pathological characteristics in lung adenocarcinoma." (PMID 35707363, 2022). "In conclusion, FAM72B may serve as a novel biomarker in predicting the clinical prognosis and immune status for lung adenocarcinoma." (PMID 35707363, 2022).
lung carcinoma (1 paper, 2022). "We further explore the diagnostic significance of FAM72B in lung cancer; a ROC curve analysis was performed." (PMID 35707363, 2022). "The results suggested that the upregulated FAM72B level is associated with a poor clinical outcome in patients with lung cancer." (PMID 35707363, 2022). "We showed that the upregulation of FAM72B expression was related to adverse clinical outcomes in patients with lung cancer." (PMID 35707363, 2022). "In this study, by adopting bioinformatics methodology and experimental verification, we found that FAM72B was upregulated in lung cancer tissues and cell lines, and a higher FAM72B level predicted an unfavorable clinical outcome in LUAD patients." (PMID 35707363, 2022).
prostate adenocarcinoma (1 paper, 2025). "Previous studies have demonstrated that FAM72B, located at 1p11.2 of the chromosome, can function as a diagnostic and prognostic biomarker for various solid tumors, including LUAD, OSCC, and prostate adenocarcinoma (PRAD)." (PMID 41153357, 2025).
triple-negative breast carcinoma (1 paper, 2025). An invasive breast carcinoma which is negative for expression of estrogen receptor (ER), progesterone receptor (PR), and human epidermal growth factor receptor 2 (HER2). "Additionally, subsets of triple-negative breast cancer (TNBC) cells expressing FAM72B have been preliminarily identified as being resistant to paclitaxel, suggesting that FAM72B may play a crucial role in tumor resistance mechanisms." (PMID 41153357, 2025).
cancer (4 papers, 2021 to 2025). A tumor composed of atypical neoplastic, often pleomorphic cells that invade other tissues. "We examined the frequency of genetic alterations in FAM72B across various cancers, as well as the specific sites and types of mutations within the FAM72B gene using the cBioPortal database." (PMID 41153357, 2025). "In our study, single-cell sequencing results indicated significant associations between FAM72B and the biological functional states of various cancers." (PMID 41153357, 2025). "The findings demonstrated that FAM72B expression was significantly linked to the infiltration levels of multiple immune cells in 43 cancer types, excluding UCS." (PMID 41153357, 2025). "Subsequently, we investigated the association of FAM72B mRNA expression with the infiltration levels of various immune cells in pan-cancer." (PMID 41153357, 2025). "FAM72B may contribute to the formation and maintenance of cancer stem cells, thereby increasing the risk of tumor recurrence and metastasis and leading to poor prognosis." (PMID 41153357, 2025). "We further evaluated the correlation between FAM72B gene mutations and cancer prognosis." (PMID 41153357, 2025). "The high expression of FAM72B in LIHC may be associated with the characteristics of cancer stem cells." (PMID 41153357, 2025). "Our findings indicate that FAM72B is likely to serve as a potential prognostic biomarker and therapeutic target for diverse cancers." (PMID 41153357, 2025). "We investigated the relation between genomic heterogeneity and FAM72B gene expression in pan-cancer from the perspectives of TMB and NEO, with the aim of identifying appropriate immunotherapies for the prognosis of cancer patients." (PMID 41153357, 2025). "To clarify the expression correlations of the FAM72B gene in various cancer types, we explored its functional states using the CancerSEA database." (PMID 41153357, 2025). "We found that, compared with normal adjacent tissues, FAM72B is overexpressed in the majority of cancers, including PRAD and GBM, which is consistent with previous research findings; however, its expression is downregulated in THCA and KICH." (PMID 41153357, 2025). "This study found that FAM72B expression is generally positively correlated with the expression of most immune checkpoint genes across pan-cancers, particularly for HMGB1, which showed a positive relation to all except for READ, COADREAD, and COAD." (PMID 41153357, 2025). "Because of the small number of normal tissues in the TCGA database, we combined this database and the GTEx database using the pan-cancer platform SangerBox3.0 to analyze the FAM72B expression in 34 types of human cancers." (PMID 41153357, 2025). "The results demonstrated that the mRNA expression levels of FAM72B were significantly upregulated in 30 types of cancer compared to their corresponding paraneoplastic tissues, while they were downregulated in THCA and KICH." (PMID 41153357, 2025). "In summary, using multiple authoritative bioinformatics technologies, we comprehensively investigated FAM72B’s expression patterns, prognostic significance, and immunomodulatory functions in pan-cancer." (PMID 41153357, 2025). "This study aimed to systematically investigate the expression profile of FAM72B in pan-cancer, its role in the tumor immune microenvironment, and its potential as a prognostic and immunotherapeutic biomarker." (PMID 41153357, 2025). "A total of 28 cancer types displayed varying degrees of alterations in the FAM72B gene among the 32 tumor types cataloged in the TCGA database." (PMID 41153357, 2025). "To determine the mRNA expression pattern of FAM72B in diverse cancer types, we used TCGA and GTEx datasets in conducting an analysis." (PMID 35707363, 2022). "We found that FAM72B expression was significantly higher in 15 of the 18 cancers compared with normal tissue." (PMID 35707363, 2022).
cancer (continued). "We further determine FAM72B expression in paired cancer tissues and adjacent normal tissues by utilizing the TCGA datasets." (PMID 35707363, 2022). "In this project, we found a high level of FAM72B in various human cancers by analyzing the GTEX and TCGA cohorts." (PMID 35707363, 2022). "The results indicated that FAM72B was highly expressed in 25 of the 33 cancers compared with normal tissue." (PMID 35707363, 2022). "Overall, these results validated the significance of FAM72B in prognostic assessment for certain cancers, indicating its potential as a prognostic biomarker, with the differential prognostic values of its expression alterations being cancer type-specific." (PMID 41153357, 2025). "However, the prognostic value and potential functions of FAM72B in the pan-cancer immune microenvironment remain to be elucidated." (PMID 41153357, 2025). "Therefore, in our study, we revealed that the expression levels of FAM72B are positively correlated with the levels of TMB, MSI, and NEO in most cancers, suggesting a possible higher response rate to ICIs among patients with high FAM72B expression." (PMID 41153357, 2025). "Notably, the upward trend in expression accompanying the increased grading of HNSC, UCEC, PAAD, GBM, GBMLGG, and OV implies a potential role for FAM72B in the disease progression of these cancers." (PMID 41153357, 2025). "Moreover, FAM72B expression was significantly correlated with the infiltration levels of various immune cells in the tumor immune microenvironment across pan-cancer." (PMID 41153357, 2025). "Additionally, the correlation of FAM72B expression with the level of NEO was examined across 32 cancer types." (PMID 41153357, 2025). "However, the potential molecular mechanisms of FAM72B in cancer progression need to be explored in further studies." (PMID 35707363, 2022). "This study analyzed the expression patterns and clinical significance of FAM72B in cancers using bioinformatics techniques, thereby providing further evidence to help us better understand the importance of FAM72B in the tumor immune microenvironment across various types of cancer." (PMID 41153357, 2025). "In terms of the N category, FAM72B expression was highest in BLCA and HNSC, where the cancer had metastasized to a greater number of more distant lymph nodes." (PMID 41153357, 2025). "The overexpression of FAM72B may upregulate HMGB1 expression or enhance its functionality, indirectly influencing fibroblasts within the tumor microenvironment and facilitating the activation, migration, and proliferation of cancer-associated fibroblasts (CAFs)." (PMID 41153357, 2025). "It has been shown that FAM72B promotes NSC and cancer cell proliferation and is present in the G2/M phase of the cell cycle." (PMID 35707363, 2022). "Then, we evaluated the correlation between FAM72B expression and clinicopathological parameters, including gender, TNM stage, disease stage, and histological grade, in multiple human cancers using the pan-cancer platform SangerBox3.0." (PMID 41153357, 2025). "Although FAM72B plays a significant role in cancer, to the best of our knowledge, there have been no studies published to date regarding its pan-cancer analysis in humans." (PMID 41153357, 2025). "The results indicated that among the eight cancers with significant correlations, FAM72B expression was negatively correlated with NEO only in TGCT, while it was positively correlated in the other seven cancers, including COADREAD, COAD, PRAD, LUAD, GBMLGG, LUSC, and GBM." (PMID 41153357, 2025). "The heatmap showed that the 15 CpG sites (located on B3GALNT1, C6orf97, FAM72A, FAM72B, LIFR, OSMR, ZNF264, and ZNF543) well‐distinguished CRC from adjacent normal tissues, WBCs, and 28 other types of cancer in TCGA, as well as 23 other types of cancer in GEO." (PMID 37649326, 2023).
tumor (4 papers, 2014 to 2025). "In this finding, we analyzed FAM72B expression, prognostic value, diagnostic values, ceRNA network, and correlation with tumor immune cell infiltration in LUAD for the first time." (PMID 35707363, 2022). "Moreover, upregulated FAM72B expression was significantly associated with immune cell infiltration in the LUAD tumor microenvironment." (PMID 35707363, 2022). "However, in the N1 stage, the high expression of FAM72B may be an adaptive change to the lymph node microenvironment, facilitating tumor cell survival and proliferation, potentially associated with the reactivation of signaling pathways such as Ras/Raf/MEK/ERK." (PMID 41153357, 2025). "In detail, as for the T category, FAM72B exhibited higher expression in highly aggressive states of KIPAN, KIRC, PRAD, BRCA, ACC, LUAD, and LIHC; moreover, there was a trend of increasing FAM72B expression with progressive tumor staging in ACC, LUAD, and LIHC." (PMID 41153357, 2025). "In LUAD, the expression level of FAM72B is closely related to the infiltration of immune cells in the tumor microenvironment." (PMID 41153357, 2025). "This study offers novel insights into the functions of FAM72B in tumor development and treatment, laying the foundation for the future development of personalized treatment plans." (PMID 41153357, 2025). "To further investigate the impact of FAM72B on the mechanisms of tumor occurrence and progression, we constructed a PPI network comprising 30 FAM72B-related genes using the STRING database and subsequently exported the relevant data." (PMID 41153357, 2025). "In THCA, FAM72B expression is higher in normal tissues but downregulated in tumor tissues, with higher expression in low-invasive tumors and the highest expression in the N1 stage (lymph node metastasis)." (PMID 41153357, 2025). "Taking LIHC and UVM as examples, FAM72B may promote tumor cell proliferation in LIHC by activating cell cycle-related genes (e.g., Cyclin D1) and accelerating the cell cycle process." (PMID 41153357, 2025). "In THYM, the high expression of FAM72B may enhance the anti-tumor capacity of the immune system by promoting the infiltration of Tfh cells, thereby improving patient prognosis." (PMID 41153357, 2025). "FAM72B may also participate in the activation of signaling pathways that facilitate tumor progression, such as the PI3K/AKT/mTOR pathway." (PMID 41153357, 2025). "Furthermore, our results confirmed that most immune cells in the tumor microenvironment, including B cells, CD4+ T cells, CD8+ T cells, neutrophils, macrophages, and dendritic cells, were negatively associated with FAM72B expression in LUAD." (PMID 35707363, 2022). "These analyses point out that FAM72B may be participating in the immune response to the LUAD tumor microenvironment, particularly to B cells and CD4+ T cells." (PMID 35707363, 2022). "Using a combined geneset of these 5 remaining cell cycle-related genes (BUB1B, CCNB1, CCNB2, TTK and CDK1) as well as ADAM7 and FAM72B, we also observed a statistically-significant reduction in disease-free survival of patients with tumours exhibiting alterations in gene expression (p = 0.015)." (PMID 25519703, 2014). "In multiple tumors, the expression of FAM72B increases with the progression of tumor staging, with the most significant increases observed in KIPAN, KIRC, ACC, and PRAD, which typically indicates that this gene is associated with tumor progression and may portend a poorer prognosis." (PMID 41153357, 2025). "Considering UM as an example, the expression of FAM72B in UM is significantly negatively correlated with DNA repair, apoptosis, and DNA damage, implying that high FAM72B expression may drive tumor progression and suppress apoptosis, thereby indicating a poorer prognosis." (PMID 41153357, 2025).
tumor (continued). "By the analysis of TIMER database, we discovered that FAM72B expression in LUAD was negatively associated with the expression levels of B cells, CD4+ T cells, CD8+ T cells, neutrophils, macrophages, and dendritic cells but positively associated with tumor purity." (PMID 35707363, 2022). "In UVM, FAM72B may reshape the extracellular matrix, thereby increasing the stiffness and density of the tumor microenvironment, which in turn inhibits the infiltration of monocytes and maintains the immunosuppressive characteristics of the tumor microenvironment." (PMID 41153357, 2025). "First, although we explored the correlation between FAM72B and immune infiltration in LUAD patients, there is a lack of experiments to validate the function of FAM72B in the tumor microenvironment regulation of LUAD." (PMID 35707363, 2022). "In LUAD, FAM72B and HMGB1 may jointly activate the PI3K/AKT signaling pathway, thereby promoting the proliferation and survival of tumor cells." (PMID 41153357, 2025). "Survival analysis identified a statistically-significant reduction in disease-free survival of patients with tumours exhibiting alterations in expression of this geneset (p = 0.023) which was lost when FAM72B and ADAM7 were removed from the geneset (p > 0.05) (data not shown)." (PMID 25519703, 2014).
FAM72B also shares sentences with these, for which no sentence is quoted: breast adenocarcinoma (1 paper); breast carcinoma (1); esophageal squamous cell carcinoma (1); glioblastoma (1); melanoma (1); mesothelioma (1); ovarian carcinoma (1); prostate tumours (1); retinoblastoma (1); sarcoma (1); skin cutaneous melanoma (1); thymoma (1); uveal melanoma (1).